RN7SL483P (RNA, 7SL, cytoplasmic 483, pseudogene)
Gene: Miscellaneous RNA gene on chromosome 12 (94,515,476 to 94,515,760, forward strand). Ensembl gene ENSG00000244091.
Homologues: Orthologues: chimpanzee Metazoa_SRP (98% identical), macaque Metazoa_SRP (88% identical). Paralogues in human: RN7SL1 (87% identical), RN7SL2 (86% identical), RN7SL3 (85% identical), RN7SL122P (82% identical), RN7SL126P (82% identical), RN7SL45P (82% identical), RN7SL660P (81% identical), RN7SL125P (81% identical), RN7SL147P (81% identical), RN7SL170P (81% identical), RN7SL386P (81% identical), RN7SL478P (81% identical), and 700 more.